EVI2B (ecotropic viral integration site 2B)
Description:
Required for granulocyte differentiation and functionality of hematopoietic progenitor cells through the control of cell cycle progression and survival of hematopoietic progenitor cells.
Synonyms: CD361; EVDB; D17S376
Tractability: Antibody: its Gene Ontology location is reachable by antibodies, with high confidence; UniProt predicts a signal peptide or a membrane-spanning region; the Human Protein Atlas places it where antibodies can reach. PROTAC: ubiquitination databases record sites on it; its protein half-life has been measured.
Gene: Protein-coding gene on chromosome 17 (31,303,770 to 31,314,421, reverse strand). Ensembl gene ENSG00000185862.
Subcellular location: Membrane
Subcellular location (Human Protein Atlas): Plasma membrane
Gene Ontology:
Biological process: positive regulation of granulocyte differentiation; myeloid cell development; negative regulation of apoptotic process; positive regulation of neutrophil differentiation; regulation of cell cycle; regulation of stem cell division
Cellular component: plasma membrane; membrane
Genetic constraint (gnomAD): Loss-of-function variants: 8 observed, 12.16 expected, observed/expected ratio (o/e) 0.66, 90% interval 0.38 to 1.19. The upper end of that interval is the gene's LOEUF score, 1.19, which puts it in group 5 of 6, group 1 being the genes least tolerant of losing a copy. Missense variants: 484 observed, 547.16 expected, observed/expected ratio (o/e) 0.88, 90% interval 0.82 to 0.95. Synonymous variants: 181 observed, 197.65 expected, observed/expected ratio (o/e) 0.92, 90% interval 0.81 to 1.04.
Homologues: Orthologues: chimpanzee EVI2B (98% identical), macaque EVI2B (92% identical), dog EVI2B (76% identical), pig EVI2B (73% identical), guinea pig EVI2B (69% identical), rabbit EVI2B (66% identical), mouse Evi2b (58% identical), rat Evi2b (55% identical).
Diseases named in the same sentence as EVI2B in open-access papers:
EVI2B is named in the same sentence as 21 diseases in open-access papers, as found by Europe PMC text mining. Sharing a sentence is not in itself a finding about the gene and the disease. The quoted sentences say what the papers report.
colorectal cancer (5 papers, 2014 to 2023). A primary or metastatic malignant neoplasm that affects the colon or rectum. "In colorectal cancer, one study showed that EVI2B was one of the hub gene sets associated with tumor progression." (PMID 34439264, 2021). "EVI2B is one of the lymphocyte-specific attractor metagenes in multiple tumor samples such as breast cancer, colorectal adenocarcinoma, and ovarian cancer and predictive of progression in colorectal cancer." (PMID 34439264, 2021). "It has been found that low expression of EVI2B could enhance cell proliferation, invasion and migration in colorectal cancer cells and remarkably promote tumor growth." (PMID 33384961, 2020). "EVI2B is expressed in peripheral blood mononuclear cells, fibroblasts, and bone marrow and blood-based overexpression of this gene was recently reported in postoperative relapse of colorectal cancer." (PMID 24479488, 2014). "Similarly, EVI2B was a potential prognostic biomarker for colorectal cancer (CRC)." (PMID 33384961, 2020).
osteosarcoma (4 papers, 2020 to 2023). A usually aggressive malignant bone-forming mesenchymal neoplasm, predominantly affecting adolescents and young adults. "EVI2B that possessed the predictive potential on prognosis was associated with metastasis and immune cell infiltration in osteosarcoma." (PMID 34630511, 2021). "Five of the seven immune-related genes (CDCA7, GZMA, SLC7A7, VAMP8, and EVI2B) were highly expressed in the osteosarcoma group, while two of these immune-related genes (IFITM3 and ACTA2) were lowly expressed." (PMID 33384961, 2020). "The heatmap of these seven immune-related genes expression level in GSE42352 indicated that five of these genes (CDCA7, GZMA, SLC7A7, VAMP8, and EVI2B) were highly expressed in the osteosarcoma group, but two of these genes (IFITM3 and ACTA2) were highly expressed in the normal group." (PMID 33384961, 2020). "The four osteosarcoma cell lines generally exhibited higher TCEA3 expression and lower PRKACB, AIM1, and EVI2B compared with the osteoblast cell line (hFOB1.19)." (PMID 36275664, 2022).
melanoma (3 papers, 2021 to 2025). A malignant, usually aggressive tumor composed of atypical, neoplastic melanocytes. "Since melanoma can be enriched with infiltrating lymphocytes, EVI2B could have a potential association." (PMID 34439264, 2021). "Our data showed that EVI2B is closely associated with multiple sets of TILs and immunomodulatory genes; therefore, in this new era of immune oncology (IO), EVI2B could be a potentially interesting target for IO research in melanoma." (PMID 34439264, 2021). "We validated the expression of DUSP1, SLAMF7 and EVI2B in human melanoma cell UACC62 and UACC257 after 8 Gy gamma-ray." (PMID 39687627, 2024). "Melanoma tumors with higher EVI2B mRNA levels were characterized by a brisk pattern of TIL distribution with increased infiltration of multiple TILs, including CD8+ T cells." (PMID 34439264, 2021). "However, the prognostic value of EVI2B expression in metastatic melanoma tissue and its detailed profile of tumor-infiltrating lymphocytes are still unclear." (PMID 34439264, 2021). "Conversely, EVI2B, a single‐pass type I transmembrane glycoprotein, was reportedly involved in tumor immunity, since the cytotoxic activity of CD8+ T cells was intensified in melanoma patients with its higher expression." (PMID 40022573, 2025). "More importantly, EVI2B was confirmed to increase CD8+ T cells over regulatory T cells and its expression correlated with multiple immunomodulatory genes including IFN-γ signature genes in melanoma." (PMID 39687627, 2024). "The melanoma immunotherapy dataset PRJEB23709(n=91), GSE100797(n=25), GSE78220(n=28), GSE91061(n=109), Nathanson_2017(n=24), phs000452(n=153) were included to analyze the influence of DUSP1, CXCL13, SLAMF7 and EVI2B in immunotherapy response." (PMID 39687627, 2024).
leukaemias (2 papers, 2022 to 2023). "It was initially discovered as a common virus incorporation site in murine retrovirally-induced leukaemias, indicating that Evi2b might be a proto-oncogene." (PMID 37533672, 2022).
metastatic melanoma (2 papers, 2021 to 2023). A melanoma that has spread from its primary site to another anatomic site. "In conclusion, EVI2B is a prognostic biomarker with IFN-γ associated immune infiltration in metastatic melanoma." (PMID 34439264, 2021). "The current study adds a potential explanation for a favorable role of EVI2B in metastatic melanoma and shows that a higher EVI2B gene expression was associated with both increased TILs and favorable spatial arrangement of TILs." (PMID 34439264, 2021). "In this study, we investigated the prognostic value of EVI2B gene expressions using the metastatic melanoma datasets from The Cancer Genome Atlas (TCGA) and Gene Expression Omnibus (GEO) datasets." (PMID 34439264, 2021). "We investigated the survival data from TCGA in metastatic melanoma patients with EVI2B gene expression." (PMID 34439264, 2021). "This study identifies the EVI2B mRNA expression as a prognostic biomarker in metastatic melanoma with IFN-γ related immune infiltration." (PMID 34439264, 2021). "Here, we report that EVI2B mRNA expression in tumor tissue was a favorable prognostic factor in metastatic melanoma patients." (PMID 34439264, 2021). "We evaluated the correlation of EVI2B gene expression in metastatic melanoma samples with the IFN-γ related gene signature (CXCL10, CXCL9, HLA-DRA, IDO1, IFNG, and STAT1)." (PMID 34439264, 2021). "A recent study has confirmed that the ecotropic viral integration site 2B (EVI2B) could be used as a new prognostic biomarker for metastatic melanoma." (PMID 37964984, 2023). "However, no study has previously investigated EVI2B as a potential biomarker in metastatic melanoma." (PMID 34439264, 2021).
myeloma (2 papers, 2022). "Consistent with our proteomic findings, in relapsed myeloma patient tumor cells we found significant transcript decreases of CD53 and EVI2B, while MME (CD10) showed a significant increase." (PMID 35840578, 2022). "In myeloma models we identify proteins that could serve as markers of resistance to bortezomib and lenalidomide, including CD53, CD10, EVI2B, and CD33." (PMID 35840578, 2022).
breast carcinoma (1 paper, 2018). "The spectrum of mutations in the NZBR lines is similar to that found in commonly used breast cancer cell lines, except that the EVI2B, LRP1B and PMS2 mutations have not been reported in breast cancer lines." (PMID 30370249, 2018).
lung adenocarcinoma (1 paper, 2024). A carcinoma that arises from the lung and is characterized by the presence of malignant glandular epithelial cells. "The results showed that IRF8, RASSF2, and EVI2B were significantly downregulated in lung adenocarcinoma tumors." (PMID 39049031, 2024). "We further investigated the expression of IRF8, CD4, RASSF2, and EVI2B in myeloid subtypes of lung adenocarcinoma." (PMID 39049031, 2024).
lung carcinoma (1 paper, 2021). "There is currently a lack of research on the relationship between EVI2B, SASH3, and PLEK with lung cancer." (PMID 34234827, 2021).
malignant peripheral nerve sheath tumor (1 paper, 2020). Malignant peripheral nerve sheath tumor (MPNST) is a rare and often aggressive soft tissue sarcoma occurring in a wide range of anatomical sites. "EVI2B enhanced the migration of NF1-associated malignant peripheral nerve sheath tumors." (PMID 32426282, 2020).
osteoarthritis (1 paper, 2023). A noninflammatory degenerative joint disease occurring chiefly in older persons, characterized by degeneration of the articular cartilage, hypertrophy of bone at the margins and changes in the synovial membrane. "Furthermore, some studies in the field of osteoarthritis have demonstrated that some bone marrow mesenchymal stem-cell-derived cells, including neutrophils (EVI2B highly expressed in OS), can affect the differentiation or function of (OBs) or osteoclasts (OCs)." (PMID 36830696, 2023).
periodontitis (1 paper, 2024). An acute or chronic inflammatory process that affects the tissues that surround and support the teeth.
renal carcinoma (1 paper, 2021). A carcinoma arising from the epithelium of the renal parenchyma or the renal pelvis. "Both KLF4 and EVI2B were identified by the Human Protein Atlas as markers for renal cancer prognoses (favorable and unfavorable, respectively)." (PMID 34108011, 2021).
tumor (11 papers, 2018 to 2025). "We validated the upregulation of EVI2B at both the mRNA and protein levels in cell lines and fresh tumor tissues (using fibroblasts and adjacent normal tissues for comparison), supporting the reliability of our findings." (PMID 36830696, 2023). "Immunohistochemical results showed that the protein levels of EVI2B in tumor tissues were higher than those in adjacent normal tissues." (PMID 36830696, 2023). "On the one hand, the high expression of EVI2B can inhibit the malignant behavior of tumor proliferation and invasion." (PMID 36065454, 2022). "Of note, we observed some EVI2B low patients (i.e., Cluster 3) that harbored NK cells in tumor tissue." (PMID 34439264, 2021). "Ecotropic viral integration site 2B (EVI2B) was significantly upregulated in OS tumor samples." (PMID 36830696, 2023). "Experimentally, we found that EVI2B inhibits tumorigenesis and tumor development." (PMID 36065454, 2022). "Thus, according to our results and consistent with the research conclusions reported, TMEM149 and EVI2B are required further study with corresponding tumor types to find better prognostic biomarkers." (PMID 32903590, 2020). "Five coexpressed genes (CD4, CD53, EVI2B, PLEK, and SASH3) were identified as tumor purity coexpressed genes that negatively correlated with tumor purity." (PMID 34234827, 2021). "The results suggested that CD4, CD53, EVI2b, PLEK, and SASH3 correlated with tumor purity, immune score, CD8+ T cells, and clinical phenotypes." (PMID 34234827, 2021). "Our data from the functional study confirmed that HCLS1, EVI2B, or CD48 suppresses CRC progression by inhibiting the proliferation, migration, and invasion capacity of CRC cells as well as tumor growth in vivo." (PMID 32426282, 2020). "Further, our data from the functional study confirmed that the overexpression of HCLS1, EVI2B, and CD48 can reduce the ability of proliferation, migration, and invasion in CRC cells and significantly suppress CRC tumor growth in vivo." (PMID 32426282, 2020). "Further, the functional study verified that over-expression of HCLS1, EVI2B, and CD48 can reduce the proliferation, migration, and invasion ability of CRC cells and significantly suppress CRC tumor growth in vivo." (PMID 32426282, 2020). "The immunostaining revealed that HCLS1, EVI2B, or CD48 proteins expression were higher in pcDNA 3.3-HCLS1, pcDNA 3.3-EVI2B, or pcDNA 3.3-CD48 compared with pcDNA 3.3-NC group in xenografted tumor." (PMID 32426282, 2020). "Furthermore, the functional study confirmed that the overexpression of HCLS1, EVI2B, and CD48 can reduce the proliferation, migration and invasion ability of CRC cells in vitro and significantly suppress CRC tumor growth in vivo." (PMID 32426282, 2020). "Notably, five DEG expression levels were correlated with prognosis in these three tumor types, including AXL, CCDC152, EVI2B, GLIPR1, and SERPING1." (PMID 32903590, 2020).
cancer (5 papers, 2020 to 2025). A tumor composed of atypical neoplastic, often pleomorphic cells that invade other tissues. "Since EVI2B is associated with a low risk for OS and may play a key role in the immune microenvironment in this cancer, we further investigated the relationship between immune cells and prognosis in 47 samples with low EVIB2 expression." (PMID 36830696, 2023). "There are few publications on the association of EVI2B with cancer prognosis." (PMID 34439264, 2021). "Moreover, for FCER1G, LGALS9, TWEM149, EVI2B, and HAMP, the gene expression levels in the cancer population were higher than those in the normal population." (PMID 32903590, 2020).
EVI2B also shares sentences with these, for which no sentence is quoted: viral infection (2 papers); asthma (1); breast invasive carcinoma (1); developmental delay (1); influenza (1); neurofibromatosis (1).